SELENOS (selenoprotein S)
Description:
Involved in the degradation process of misfolded endoplasmic reticulum (ER) luminal proteins. Participates in the transfer of misfolded proteins from the ER to the cytosol, where they are destroyed by the proteasome in a ubiquitin-dependent manner. Probably acts by serving as a linker between DERL1, which mediates the retrotranslocation of misfolded proteins into the cytosol, and the ATPase complex VCP, which mediates the translocation and ubiquitination.
Synonyms: SelS; VIMP; AD-015; SBBI8; MGC2553; SEPS1; ADO15
Tractability: Small molecule: a structure with a bound ligand is known. Antibody: its Gene Ontology location is reachable by antibodies, with high confidence; UniProt predicts a signal peptide or a membrane-spanning region. PROTAC: UniProt records ubiquitination sites on it; ubiquitination databases record sites on it.
Gene: Protein-coding gene on chromosome 15 (101,270,531 to 101,277,500, reverse strand). Ensembl gene ENSG00000131871.
Subcellular location: Endoplasmic reticulum membrane; Cytoplasm
Subcellular location (Human Protein Atlas): Endoplasmic reticulum
Pathways (Reactome):
Metabolism of proteins: E3 ubiquitin ligases ubiquitinate target proteins
Gene Ontology:
Molecular function: antioxidant activity; ATPase binding; enzyme binding; protein binding; ubiquitin-specific protease binding; signaling receptor activity
Biological process: cell redox homeostasis; cellular response to lipopolysaccharide; cellular response to oxidative stress; endoplasmic reticulum unfolded protein response; ER overload response; ERAD pathway; negative regulation of acute inflammatory response to antigenic stimulus; negative regulation of endoplasmic reticulum stress-induced intrinsic apoptotic signaling pathway; negative regulation of macrophage apoptotic process; regulation of nitric oxide metabolic process; response to glucose; response to redox state; retrograde protein transport, ER to cytosol; cellular response to insulin stimulus; establishment of protein localization; negative regulation of D-glucose import; negative regulation of glycogen biosynthetic process; negative regulation of inflammatory response; negative regulation of interleukin-6 production; negative regulation of tumor necrosis factor production; regulation of gluconeogenesis; cellular oxidant detoxification; intracellular protein transport
Cellular component: cytoplasmic microtubule; Derlin-1 retrotranslocation complex; Derlin-1-VIMP complex; endoplasmic reticulum; endoplasmic reticulum membrane; low-density lipoprotein particle; very-low-density lipoprotein particle; plasma membrane; cytoplasm
Genetic constraint (gnomAD): Loss-of-function variants: 37 observed, 27.62 expected, observed/expected ratio (o/e) 1.34, 90% interval 1.03 to 1.75. The synonymous counts are far from expectation, so gnomAD's model fits this gene poorly and the ratio says little. Missense variants: 289 observed, 215.3 expected, observed/expected ratio (o/e) 1.34, 90% interval 1.22 to 1.48. Synonymous variants: 119 observed, 86.04 expected, observed/expected ratio (o/e) 1.38, 90% interval 1.19 to 1.61.
Homologues: Orthologues: dog SELENOS (92% identical), pig SELENOS (88% identical), guinea pig SELENOS (87% identical), mouse Selenos (84% identical), chimpanzee SELENOS (82% identical), rat Selenos (74% identical), tropical clawed frog selenos (51% identical).